IRF6 (interferon regulatory factor 6)
Diseases named in the same sentence as IRF6 in open-access papers (continued):
Sharing a sentence is not in itself a finding about the gene and the disease.
cleft lip (continued). "The purpose of this systematic review was to utilize a zebrafish model to highlight the role of the IRF6 gene in cleft lip and palate development in humans." (PMID 38533046, 2024). "The main outcome supports the role of the IRF6 gene in zebrafish periderm development and embryogenesis, and IRF6 variations result in cleft lip and palate development." (PMID 38533046, 2024). "IRF6 is highly expressed in epithelial cells and mutations in IRF6 are responsible for Van der Woude (VWS) and popliteal pterygium syndrome (PPS), two autosomal dominant forms of cleft lip and palate." (PMID 23451037, 2013). "It has been suggested to be an important contributor to orofacial development since mutations of the IRF6 gene has been found in Van der Woude (VWS) and popliteal pterygium syndromes (PPS), two disorders that can present with isolated cleft lip and palate." (PMID 23510002, 2013). "Analysis of the pooled samples indicates statistical interaction between a marker at TGFA (rs1807968) and another marker at IRF6 (rs2013162) in the cleft lip only group (P = 0.003)." (PMID 23029012, 2012). "Since tooth agenesis is commonly found in individuals with cleft lip/palate (CL/P), we used four large cohorts to evaluate if IRF6 and TGFA interaction contributes to CL/P." (PMID 23029012, 2012). "Since tooth agenesis is commonly found in individuals with cleft lip/palate, we used three large samples of cleft cases to test for interaction between IRF6 and TGFA in the etiology of the cleft phenotype." (PMID 23029012, 2012). "Markers located within and flanking the IRF6 and TGFA genes were tested for association with cleft of the lip or palate under a case-control design." (PMID 23029012, 2012). "A recent study identified a number of highly-conserved elements surrounding the IRF6 gene which is known to be involved in several types of syndromic and non-syndromic cleft lip/palate." (PMID 20808887, 2010). "Therefore, this systematic review provides evidence supporting the role of the IRF6 gene and its downstream targets in cleft lip and palate etiology in a zebrafish model." (PMID 38533046, 2024). "We used the gene IRF6 as a case study due to its clinical relevance, its critical role in cleft lip/palate malformation, and the availability of experimental data on the pathogenicity of IRF6 gene variants through phenotype rescue experiments in irf6-/- zebrafish." (PMID 38370976, 2024). "Certain SNP mutations in the IRF6 gene have been significantly correlated with the presence of cleft lip with or without cleft palate (CL/P) in various populations." (PMID 37762190, 2023). "Therefore, the IRF6 gene is considered important in the study of dental development disorders due to its confirmed role in the etiology of cleft lip and palate." (PMID 37762190, 2023). "Nevertheless, CL/P and CP can segregate in the same family, with etiologic mutations in genes such as FGFR1, IRF6, MSX1 and P63, and epidemiologic data suggest that cleft lip only may have unique etiologic features." (PMID 31652620, 2019). "p63 may directly activate Irf6 in the facial ectoderm, and a defective pre-B cell leukemia homeobox (Pbx)-Wnt-p63-Irf6 signaling cascade has been suggested in cleft lip formation." (PMID 30760477, 2019). "IRF6 rs2235375 variant was significantly associated with increased risk of non-syndromic cleft lip with or without palate in co-dominant, dominant (OR: 1.19; 95% CI 1.03–2.51; p = 0.034) and allelic models (OR: 1.40; 95% CI 1.04–1.90; p = 0.028)." (PMID 28712851, 2018). "In this study, we extend our previous work to evaluate the association between IRF6 Intron-6 dbSNP208032210:g.G>C (rs2235375) single nucleotide polymorphism with non-syndromic cleft lip with or without palate risk in South Indian Population." (PMID 28712851, 2018).
cleft lip (continued). "The association between interferon regulatory factor-6 gene intron-6 dbSNP208032210:g.G>C (rs2235375) single nucleotide polymorphism and non-syndromic cleft lip with or without palate risk was investigated by chi-square test." (PMID 28712851, 2018). "We aimed to investigate the association of IRF6 intron-6 polymorphism in the non-syndromic cleft lip with or without palate in a South Indian population." (PMID 28712851, 2018). "We conducted a systematic review and meta‐analysis of interferon regulatory factor 6 and 8q24 polymorphisms with nonsyndromic cleft lip with/without cleft palate (NSCL/P)." (PMID 27511269, 2016). "It has been suggested to be important contributor to orofacial development since mutations of the IRF6 gene have been found in Van der Woude (VWS) and popliteal pterygium syndromes (PPS), two disorders that can clinically resemble an isolated cleft lip and palate." (PMID 23510002, 2013). "We speculated on the attributable fraction for the interaction of IRF6 and TGFA genes to the risk of cleft lip/palate using the Brazilian case-control sample and three additional family or case series data sets comprising a total of 8,717 individuals." (PMID 23029012, 2012). "In addition to IRF6, v-maf musculoaponeurotic fibrosarcoma oncogene homolog B (MAFB) and intron 6 of the ATP-binding cassette subfamily A member 4 (ABCA4) also contribute to the risk of cleft lip and palate." (PMID 26322076, 2015). "In addition to VWS and PPS, mutations in IRF6 have been associated with non-syndromic cleft lip with or without cleft palate." (PMID 26240017, 2015). "Interestingly, a genetic variant from IRF6 gene, which is also a well-known risk factor of non-syndrome cleft lip, was found to strongly predispose the mouth shape in Han Chinese females." (PMID 24339768, 2013). "In conclusion, this review indicated the critical role of the IRF6 gene and its downstream genes (GRHL3, KLF17, and ESRP1/2) in the development of cleft lip and palate in zebrafish models." (PMID 38533046, 2024). "Taken together, our systematic review indicated the critical role of the IRF6 gene and its downstream genes (GRHL3, KLF17, and ESRP1/2) in the development of cleft lip and palate in zebrafish models." (PMID 38533046, 2024). "Incomplete penetrance in cleft lip and palate (CLP) exemplifies the phenomenon where individuals carrying mutations in specific genes, such as IRF6, MSX1, and TP63, do not consistently express the associated phenotype." (PMID 39506048, 2025). "IRF6 rs2235375 showed a significant association with an increased risk for non-syndromic cleft lip and palate (NSCLP) and cleft lip with or without cleft palate (NSCL/P) in the G allele, with pallele values of 0.0018 and 0.0003, respectively." (PMID 38002937, 2023). "Therefore, we hypothesized interaction between IRF6 and TGFA may also be relevant to cleft lip/palate." (PMID 23029012, 2012). "Therefore interaction between IRF6 and TGFA in tooth agenesis may also be relevant to cleft lip/palate." (PMID 23029012, 2012).
orofacial cleft (31 papers, 2006 to 2025). A disorder of facial skeleton that is characterized by cleft lip and/or cleft palate that result in feeding, speech and hearing problems caused by failures during development. "Support for our findings comes from a previous study examining candidate SNPs in the IRF6 region which found that rs126280 was the driver of associations between IRF6 haplotypes and orofacial clefts." (PMID 41075272, 2025). "Our reported case carrying a novel mutation can contribute to expand understandings of molecular mechanisms underlying synechiae and orofacial clefting and to correct diagnosing of incomplete or overlapping features in IRF6-related disorders." (PMID 35906647, 2022). "Yet, studying IRF6 in human cells is important since IRF6 variants are associated with non-syndromic CLP cases as well as causative for two syndromic forms of orofacial clefting, VWS and PPS." (PMID 34660580, 2021). "The aim of this study was to investigate the association of IRF6 polymorphisms with non-syndromic orofacial clefts development in a population from northeast Brazil." (PMID 31495697, 2020). "Already, the human orthologs of four known elements of this GRN, Irf6, Grhl3, Klf17, and simple epithelium keratins, are implicated in risk for non-syndromic orofacial clefting." (PMID 32031521, 2020). "While coding mutations of IRF6 can cause syndromic OFC, polymorphisms near IRF6 are overtransmitted in patients with non-syndromic orofacial clefting (NSOFC)." (PMID 32582293, 2020). "Among the more than 15 susceptibility loci for non-syndromic orofacial clefts with considerable statistical and biological support, the IRF6 is the most validated gene by the majority of studies." (PMID 31495697, 2020). "IRF6 disruption is causal for syndromic cleft in Van der Woude and popliteal pterygium syndromes, and associated with non-syndromic orofacial clefts." (PMID 33234718, 2020). "Blood samples of 186 non-syndromic orofacial clefts patients and 182 controls from Rio Grande do Norte, Brazil, were obtained to analyze IRF6 polymorphisms (rs2235371, rs642961, rs2236907, rs861019, and rs1044516) by real-time polymerase chain reaction." (PMID 31495697, 2020). "Here, we utilized a zebrafish model to rapidly evaluate the protein functions of rare gene variants of IRF6, a gene of established importance in orofacial cleft pathogenesis." (PMID 28945736, 2017). "The aim of this study was to show evidence of potentially pathogenic variants in IRF6 in orofacial clefts cohorts from Africa." (PMID 28361103, 2017). "One well-studied example of a common congenital malformation associated with gene variants is that of orofacial clefts associated with the transcription factor Interferon Regulatory Factor 6 (IRF6, ENSG00000117595)." (PMID 28945736, 2017). "Interferon Regulatory Factor 6 (IRF6) gene variants are significant genetic contributors to orofacial clefts." (PMID 28945736, 2017). "For example, in individuals with nonsyndromic orofacial clefts, the major allele for common polymorphisms in IRF6 and FOXE1 are over-represented." (PMID 22140583, 2011). "For example, some genes with mutations that could lead to human orofacial clefts, such as IRF6 and WNT9A, showed a consistent phenotype in the ethmoid plate, indicating a well‐conserved function in palatogenesis in mice and zebrafish." (PMID 39320016, 2025). "Successively, a targeted gene panel sequencing (480 genes for orofacial clefts) revealed a novel de novo heterozygous c.262A > G mutation in exon 4 of IRF6 gene (OMIM *607,199) causing an asparagine to aspartate missense mutation (p.Asn88Asp) that was compatible with the phenotype." (PMID 35906647, 2022). "In addition, IRF6 variants have also been found associated with isolated, non-syndromic orofacial clefts." (PMID 34660580, 2021).
orofacial cleft (continued). "From genome-wide association studies carried out over a decade ago to more recent whole-genome sequencing projects of orofacial cleft cohorts, cleft-associated genetic loci continue to be identified, and the transcription factor IRF6 is one of the most commonly associated genes." (PMID 33234718, 2020). "Furthermore, it unlocked the possibility for characterizing yet undiscovered human IRF6 missense gene variants from orofacial cleft patients, and illustrated a generalizable functional genomics paradigm in personalized medicine." (PMID 28945736, 2017). "This study demonstrates that exons 4 and 7 of IRF6 are mutational ‘hotspots’ in our cohort and that IRF6 mutants‐induced orofacial clefts may be prevalent in the Africa population, however, with variable penetrance and expressivity." (PMID 28361103, 2017). "Interestingly, genetic interactions between TGFA and IRF6 (i.e. co-transmission of risk alleles with higher than expected frequency) were reported to contribute to the risk for tooth agenesis as well as orofacial clefts." (PMID 25360592, 2014). "Meta analysis of mutation-proved IRF6-related phenotypes might provide another useful indicator for the diagnosis of orofacial cleft in the near future." (PMID 23510002, 2013). "IRF6 may be one such gene associated with non-syndromic orofacial clefts." (PMID 40083395, 2025). "However, whether orofacial cleft-associated IRF6 and GRHL3 variants in patients might also affect their cancer risk later in life, is not clear yet." (PMID 36457487, 2022). "Numerous pathological variants within IRF6 and GRHL3 have been identified in orofacial cleft-affected individuals and expression of the two transcription factors has been found to be often dysregulated in cancers." (PMID 36457487, 2022). "This work highlights the relative strengths of the mouse and zebrafish models for investigating the morphogenetic mechanisms of orofacial clefts, and contributes new insights into the function of Irf6 and Esrp1/2 during palatogenesis." (PMID 33234718, 2020). "Interferon Regulatory Factor 6 (IRF6) (OMIM:607199) gene has been associated with the etiology of both syndromic and nonsyndromic orofacial clefts." (PMID 28361103, 2017). "Mutations in the IRF6 and GRHL3 genes can lead to VWS, with a dysfunctional oral periderm contributing to the phenotypes of orofacial clefts in humans." (PMID 27459192, 2016). "Of the large number of candidate genes thought to contribute to orofacial clefting, Interferon Regulatory Factor 6 (IRF6) is the only gene that has shown a convincing degree of consistency across studies." (PMID 23510002, 2013). "Importantly, IRF6—a gene involved in orofacial clefting —has previously been identified as a critical AP-2 target." (PMID 35333176, 2022). "Nonetheless, in genetically heterogeneous populations such as Brazilian, the confirmation of association between non-syndromic orofacial clefts and IRF6 common variants is not a consolidated fact and unrecognized IRF6 variants are poorly investigated." (PMID 31495697, 2020). "While these non-synonymous homozygous ADGRA2, EGF, F13A1, IRF6, and GSTP1 genes mutation might encode mutant proteins, they do not provide a prediction of the phenotype, but may contribute to more accurate assessments of the orofacial clefts or hypospadias." (PMID 37238140, 2023). "Our study substantially expands the knowledge of IRF6 function in postnatal human keratinocytes and will be important for a better understanding of VWS and/or general orofacial cleft-related complications or other IRF6-related pathologies." (PMID 34660580, 2021). "TGFA has also been associated with orofacial clefts, and a previous study using the case-parent trio design raised the possibility that IRF6 and TGFA interact and lead to orofacial clefts, supporting the finding from our group." (PMID 33406080, 2021).
orofacial cleft (continued). "We show that IRF6 and ESRP1 are conserved in their requirement for ANC morphogenesis, where disruption results in orofacial cleft in human, mouse and zebrafish." (PMID 33234718, 2020). "The manipulability, minimal cost and susceptibility of chicks to CL/P will enable more detailed investigations into how perturbations of IRF6, LHX6 and LHX7 contribute to common orofacial clefts." (PMID 16563169, 2006).
popliteal pterygium syndrome (31 papers, 2006 to 2025). A rare, autosomal dominant inherited syndrome caused by mutations in the IRF6 gene. "IRF6 pathogenic variants were also detected in nonsyndromic cleft lip and palate and popliteal pterygium syndrome (PPS; OMIM # 119500)." (PMID 37628654, 2023). "A one-month-old Moroccan baby boy was diagnosed with typical features of popliteal pterygium syndrome and carried the c.250C>T; p.Arg84Cys mutation of the IRF6 gene." (PMID 25547932, 2014). "IRF6 is mutated in Van der Woude and Popliteal pterygium syndromes and has recently been identified as one of the most significant non-syndromal CL/P loci to date." (PMID 16563169, 2006). "Recently, mutations in the IRF6 (Interferon Regulatory Factor 6) gene were shown to cause the allelic disorders, Van der Woude and Popliteal pterygium syndromes, both of which have CL/P as a major clinical feature." (PMID 16563169, 2006). "Popliteal pterygium syndrome (PPS; MIM #119500), also results from mutations in IRF6 and has a similar orofacial phenotype to VWS but exhibits additional anomalies that include popliteal webbing, pterygia, oral synychiae, adhesions between the eyelids, syndactyly and genital anomalies." (PMID 32582293, 2020). "Pathogenic variants in IRF6 are associated with complex syndromes such as non-syndromic cleft lip and palate (NSCLP), Popliteal Pterygium Syndrome (PPS), and Von der Woude Syndrome (VDWS)." (PMID 40149423, 2025). "Moreover, genetic mutations in IRF6 or CHUK have been identified in individuals clinically diagnosed with Bartsocas-Papas syndrome, a form of popliteal pterygium syndrome, supporting the global notion that Irf6 and components of the NFkB pathway are part of the same gene regulatory network." (PMID 27035130, 2016). "The study identified 46 mutations in IRF6 in patients with VWS and another 13 in patients with popliteal pterygium syndrome (PPS; MIM 119500)." (PMID 23915469, 2013). "Lack of IRF6 expression may implicate birth defects such as VWS and popliteal pterygium syndrome." (PMID 37020525, 2023).
cleft palate (26 papers, 2009 to 2026). Cleft palate is a fissure type embryopathy that affects the soft and hard palate to varying degrees. "Disruption of periderm, as observed in Irf6-deficient or Grhl3-deficient mice, can cause abnormal oral adhesion and ultimately result in cleft palate." (PMID 40037804, 2025). "In this study, we observed that deficiencies in Irf6 can lead to mandibular hypoplasia and cleft palate." (PMID 28769044, 2017). "The ChIP-seq data also identified p63-bound regions associated with Pvrl1, Irf6, Fgfr2, Tcfap2a, Pdgfa, Sfn, Grhl3 and Jag2, mutations in which result in cleft palate." (PMID 28604778, 2017). "For example, a nucleotide duplication in an enhancer of IRF6 has been implicated in cleft palate." (PMID 37364051, 2023). "Thus, for example, the C>T functional single nucleotide polymorphism (SNP) 14.5 kb upstream of the interferon regulatory factor 6 (IRF6) gene, which is associated with cleft palate, alters the binding of transcription factor AP-2α." (PMID 23947441, 2013). "IRF6 was also associated with cleft palate (CP) with impaction of permanent teeth (p<10−6)." (PMID 23029012, 2012). "Additionally, variants in IRF6 were found in cases of non‐isolated RS with cleft palate." (PMID 41077824, 2026). "Mutations in IRF6 cause Van der Woude's, along with popliteal pterygium, and recent research suggests that mutations surrounding the gene may be involved in non-syndromic cleft palate." (PMID 26973535, 2016). "For these two groups, rs227731 (17q22), rs8610209 (IRF6), and rs2514527 (GDF6) were selected as risk predictors for cleft palate-soft only, whereas rs2073485 (IRF6), rs17389541 (IRF6), and rs1530300 (8q24) jointly contributed to the risk of cleft palate-hard." (PMID 26322076, 2015). "Notably, Irf6, which is a gene that induces cleft palates in mice and humans, is sometimes expressed within the embryonic maxillary process of zebrafish and serves a similar role between all three species." (PMID 39320016, 2025). "Recent research has shown that IRF6 mutant mice exhibit a hyper-proliferative epidermis that fails to undergo terminal differentiation, which leads to multiple epithelial adhesions that can occlude the oral cavity and result in cleft palate." (PMID 28712851, 2018). "Since more SNPs located within one gene, a total of 34 epithelial genes have been identified, in which IRF6 has been reported as a contributor to cleft palate, while other genes have not been reported to be associated with CP." (PMID 36008388, 2022). "Several genetic polymorphisms of IRF6 have been associated with NSOFC risk in many populations, including Non-Syndromic Cleft Lip with or without cleft Palate (NSCL/P) subtype." (PMID 31495697, 2020).